CA2 (carbonic anhydrase 2)
Description:
Catalyzes the reversible hydration of carbon dioxide. Can also hydrate cyanamide to urea. Stimulates the chloride-bicarbonate exchange activity of SLC26A6. Essential for bone resorption and osteoclast differentiation. Involved in the regulation of fluid secretion into the anterior chamber of the eye. Contributes to intracellular pH regulation in the duodenal upper villous epithelium during proton-coupled peptide absorption.
Synonyms: CAC; CA-II; Car2; CAII; HEL-76; HEL-S-282
Tractability: Small molecule: an approved drug acts on it; a structure with a bound ligand is known; a high-quality ligand is known; it has a high-quality binding pocket; it belongs to a druggable protein family. Antibody: UniProt places it where antibodies can reach, with high confidence; its Gene Ontology location is reachable by antibodies, with high confidence. PROTAC: ubiquitination databases record sites on it; its protein half-life has been measured; a small molecule that binds it is known.
Target class: Enzyme; Lyase
Chemical probes: PD081103, PD082035, PD082418
Gene: Protein-coding gene on chromosome 8 (85,463,968 to 85,481,493, forward strand). Ensembl gene ENSG00000104267.
Subcellular location: Cytoplasm; Cell membrane
Pathways (Reactome):
Transport of small molecules: Erythrocytes take up carbon dioxide and release oxygen; Erythrocytes take up oxygen and release carbon dioxide
Developmental Biology: Developmental Lineage of Pancreatic Ductal Cells
Metabolism: Reversible hydration of carbon dioxide
Gene Ontology:
Molecular function: arylesterase activity; carbonate dehydratase activity; cyanamide hydratase activity; protein binding; zinc ion binding
Biological process: angiotensin-activated signaling pathway; regulation of monoatomic anion transport; positive regulation of dipeptide transmembrane transport; regulation of intracellular pH
Cellular component: apical part of cell; cytoplasm; extracellular exosome; plasma membrane; cytosol; myelin sheath
Genetic constraint (gnomAD): Loss-of-function variants: 21 observed, 20.26 expected, observed/expected ratio (o/e) 1.04, 90% interval 0.73 to 1.49. The upper end of that interval is the gene's LOEUF score, 1.49, which puts it in group 6 of 6, group 1 being the genes least tolerant of losing a copy. Missense variants: 262 observed, 274.32 expected, observed/expected ratio (o/e) 0.96, 90% interval 0.86 to 1.06. Synonymous variants: 84 observed, 98.81 expected, observed/expected ratio (o/e) 0.85, 90% interval 0.71 to 1.02.
Gene-disease validity (ClinGen):
ClinGen rates the evidence that CA2 causes each of these diseases.
autosomal recessive osteopetrosis 3 (autosomal recessive): Definitive. Osteopetrosis with renal tubular acidosis is a rare disorder characterized by osteopetrosis, renal tubular acidosis (RTA), and neurological disorders related to cerebral calcifications.
Homologues: Orthologues: macaque CA2 (98% identical), chimpanzee CA2 (97% identical), dog CA2 (87% identical), mouse Car2 (81% identical), pig CA2 (81% identical), rat Car2 (81% identical), guinea pig CA2 (78% identical), rabbit CA2 (75% identical), zebrafish cahz (63% identical), zebrafish ca2 (62% identical), tropical clawed frog ca2 (61% identical), Drosophila melanogaster CAH1 (47% identical). Paralogues in human: CA13 (60% identical), CA1 (60% identical), CA3 (58% identical), CA7 (57% identical), CA5B (53% identical), CA5A (51% identical), CA8 (40% identical), CA12 (36% identical), CA10 (35% identical), CA14 (35% identical), CA11 (34% identical), CA6 (33% identical), and 2 more.
Diseases named in the same sentence as CA2 in open-access papers:
CA2 is named in the same sentence as 259 diseases in open-access papers, as found by Europe PMC text mining. Sharing a sentence is not in itself a finding about the gene and the disease. The quoted sentences say what the papers report.
glaucoma (28 papers, 2011 to 2025). Increased pressure in the eyeball due to obstruction of the outflow of aqueous humor. "In this study, we developed a targeted therapy for glaucoma by knocking down two genes associated with aqueous humor production (aquaporin 1 [AQP1] and carbonic anhydrase type 2 [CA2]) using Cas13 RNA editing systems." (PMID 40575705, 2025). "The protocatechuic acid has 72 targets including carbonic anhydrase 2 related to glaucoma, osteoporosis, epilepsy, tumors, which is also the result of predicted target." (PMID 33482800, 2021). "During the preparation of our manuscript, another group published a study that pointed out CA2 knockout significantly and sustainably reduces IOP for up to 2 months in normal mice and glaucoma models by inhibiting aqueous humor production." (PMID 40575705, 2025). "We demonstrate that hfCas13d-mediated knockdown of AQP1 and CA2 significantly lowers IOP in wild-type mice and in a corticosteroid-induced glaucoma mouse model." (PMID 40575705, 2025).
osteopetrosis (26 papers, 2012 to 2025). Osteopetrosis, also known as marble bone disease, is a descriptive term that refers to a group of rare, heritable disorders of the skeleton characterized by increased bone density on radiographs. "Specifically, CA2 deficiency is the paradigm osteopetrosis featuring failure of osteoclasts to resorb bone due to inability to acidify their pericellular space." (PMID 40445217, 2025). "Osteopetrosis is also associated with a decrease in Car2 (carbonic anhydrase 2), which was down-regulated in 5 of 6 MPS VII brain regions." (PMID 22403656, 2012). "Extremely rare forms of osteoclast-rich osteopetrosis are caused by defects in the carbonic anhydrase 2 (CA2), pleckstrin homology and RUN domain-containing M1 (PLEKHM1), leucine-rich repeat kinase 1 (LRRK1) and melanocyte-inducing transcription factor (MITF) genes." (PMID 33970241, 2021). "Moreover, mutations of CA2 gene per se cause mixed renal tubular acidosis, with osteopetrosis and mental retardation." (PMID 32397528, 2020). "Carbonic Anhydrase II (CA2) is highly expressed in mature osteoclasts, and the mutations in CA2 cause a very mild osteopetrosis, OPTB3, with renal tubular acidosis and cerebral calcifications." (PMID 37373559, 2023). "Some studies have indicated that carbonic anhydrase 2 (CA2) defect would cause a series symptoms, including osteopetrosis with renal tubular acidosis and brain calcification." (PMID 31412925, 2019). "For instance, some mutations in carbonic anhydrase II (CA2; MIM# 611492) are uniquely related to a monogenic disease named osteopetrosis with renal tubular acidosis (MIM# 259730 or ORPHA 2785)." (PMID 25420641, 2014). "Furthermore, bone healing in individuals suffering from osteopetrosis is impaired, thus suggesting a central role of CA2 in this biological process." (PMID 40445217, 2025).
renal tubular acidosis (22 papers, 2010 to 2024). A group of genetic disorders of the kidney tubules characterized by the accumulation of metabolically produced acids with elevated plasma chloride, hyperchloremic metabolic acidosis. "Defects in carbonic anhydrase have been associated with renal tubular acidosis; thus, carbonic anhydrase 2-deficient mice, characterized by metabolic acidosis, exhibit high bacterial concentrations in the kidneys after transurethral inoculation with uropathogenic E. coli." (PMID 39063167, 2024). "For example, the disease node labelled Renal Tubular Acidosis was linked to one cytokine, three proteins and 12 RNA despite that this disease was only related to two known RNA (SLC4A1, CA2) in this network." (PMID 34883510, 2022). "SLC4A1 shares phenotypes with CA2, including periodic paralysis (HP:0003768), renal tubular acidosis (HP:0001947) and hypokalemia (HP:0002900) and is also biochemically related to CA2 by physical interactions." (PMID 25420641, 2014).
breast carcinoma (19 papers, 2002 to 2024). "Thus, we summarized the studies that have used Ca2+ channel blockers for breast cancer medication to understand the associated mechanisms." (PMID 33806911, 2021). "In Luminal A breast cancer, the cytosolic carbonic anhydrases CA1 (HR = 1.295), CA2 (HR = 1.340), and CA3 (HR = 0.753) associate significantly with survival, and a similar influence of CA2 is observed in Luminal B breast cancer (HR = 1.205)." (PMID 37098526, 2023). "Like CA1, the most common gene alterations in CA2 were amplifications especially in neuroendocrine prostate cancer, breast cancer, prostate adenocarcinomas and metastatic cancers followed by mutations." (PMID 29495652, 2018). "In 66 breast cancer biopsies, the expression of the Ca2+-binding protein S100A4, E-cadherin, α- and β-catenin was examined by immunohistochemistry, and the results were related to clinical and pathological parameters." (PMID 12439718, 2002). "Changes in the expression of other Ca2+ channels have been found in breast cancer." (PMID 36790286, 2023). "Therefore, controlling the activity of Ca2+ channels in breast tumor cells can lead to new therapeutic methods for brain metastases resulting from breast cancer." (PMID 33806911, 2021). "On the other hand, carbonic anhydrases, namely CA12, CA2, and CA1, were the major breast cancer protein targets interconnected to the identified metabolites according to their degree of involvement." (PMID 39482666, 2024). "Based on proteomic data from human biopsies, we additionally confirm the expression of cytosolic (CA1, CA2, CA3, CA13), mitochondrial (CA5β), and extracellular (CA4, CA6, CA9, CA12) carbonic anhydrases in breast cancer tissue." (PMID 37098526, 2023). "Most of the other carbonic anhydrase isoforms—especially CA1, CA2, CA3, CA9, CA12, CA13, and CA14—are expressed at highest level in breast cancer epithelial cells." (PMID 37098526, 2023). "CA2, PMA, ILQ, and cardamonin were previously shown to induce autophagy in various human tumor cells, including melanoma cells, breast cancer cells, and colon cancer cells." (PMID 27537898, 2016). "Gene targets in breast cancer samples, including CYP24A1, DPP4 and CA2, seem to be shared by both fibroblasts and epithelial cells." (PMID 23497279, 2013). "Additionally, upregulation of CA2, CNN3 and AKAP13 was found, which are suggested to be involved in chemotherapy resistance in glioblastoma, colon cancer and breast cancer, respectively." (PMID 33712646, 2021). "The potential roles for specific Ca2+ channels in these pathways were assessed by siRNA-mediated silencing of ORAI1 and transient receptor potential canonical type 1 (TRPC1) channels in MDA-MB-468 breast cancer cells." (PMID 22666335, 2012). "Lastly, carbonic anhydrase II (CA2) is one of 16 forms of human α carbonic anhydrase and has been shown to be upregulated or associated with androgen receptors in various cancer types such as meningioma and breast cancer, but not in PC." (PMID 35326723, 2022).
epilepsy (15 papers, 2015 to 2025). A brain disorder characterized by episodes of abnormally increased neuronal discharge resulting in transient episodes of sensory or motor neurological dysfunction, or psychic dysfunction. "ChrA immunoreactivity has been described in the human hippocampus, and it was proposed to be one of the underlying factors of CA2 resistance to epilepsy-induced damage." (PMID 38180568, 2024). "Since their discovery, Ca2+-permeable AMPARs (CPARs) have been implicated in the pathogenesis of various neurologic conditions, including epilepsy, amyotrophic lateral sclerosis, ischemic insult, and AD." (PMID 34290083, 2021). "Similarly, the density of PV+ cells is considerably reduced in CA2 during epilepsy, and physiological recordings in the hippocampi of human epileptic patients revealed an important decrease in inhibition of or a complete loss of inhibition of CA2 PNs." (PMID 26465002, 2015). "Given CA2’s essential role in social memory, its heightened vulnerability during this developmental window may help explain the co-occurrence of epilepsy, social cognitive impairments, and autistic-like features in some individuals." (PMID 41480494, 2025). "Disruptions in CA2 neuronal networks and/or alterations in CA2 neuronal function may mediate these co-occurring deficits, providing a crucial link between epilepsy and social cognitive impairments." (PMID 41480494, 2025). "Neither CLCN7 nor CA2 mutations have previously been reported to be associated with renal stones or epilepsy." (PMID 27540713, 2016). "It is known that changes of Na+, K+, and Ca2+ channels can all contribute to epilepsy." (PMID 26834617, 2015).
diabetes (12 papers, 2018 to 2024). "Some authors reported about Ca2+-ATPase activity of erythrocyte membranes decreased in both diabetes and in erythrocytes treated ex vivo with glucose, probably due to the glycation of Ca2+-ATPase." (PMID 32349441, 2020). "Therefore, we suggest that impaired Ca2+ homeostasis in the brain may play a role in the neurological complications of diabetes, as treatment with a Ca2+ channel blocker improves Ca2+-dependent synaptic plasticity in the hippocampus of diabetic patients." (PMID 32079069, 2020). "In the present study, we reported another Ca2+ channel signaling, SOCE, as another mechanism contributing to podocyte injury related to diabetes mellitus." (PMID 35490782, 2022). "MR blockade only partially decreased ROCK activity, suggesting that other mechanisms are also involved in MR-sensitive vascular dysfunction in diabetes, such as PKC activation and Ca2+-calcineurin pathways." (PMID 29440699, 2018).
osteoporosis (12 papers, 2018 to 2023). A condition of reduced bone mass, with decreased cortical thickness and a decrease in the number and size of the trabeculae of cancellous bone (but normal chemical composition), resulting in increased fracture incidence. "CA2 variants have been associated with various health conditions such as osteoporosis, cancer, ulcers, and obesity." (PMID 37895185, 2023). "We found only one study, also in osteoporosis, which reported that estradiol reduced the expression of CA2 in osteoporosis, which is different from our experimental findings." (PMID 34803683, 2021). "The mechanisms of inhibition were via suppression of osteoporosis-related protein expression (NFATc1 and c-Fos), gene expression (Nfatc1, Ca2, Acp5, mmp9, CtsK, Oscar, and Atp6v0d2), and inhibited bone loss induced in the OVX model." (PMID 33859705, 2021). "Therefore, we believe that HSYA can inhibit the differentiation of osteoclasts by inhibiting the expression of CA2 from achieving the therapeutic effect of osteoporosis." (PMID 34803683, 2021). "When CA2 is deficient, it has been found that nonfunctional osteoclasts cause osteoporosis." (PMID 35058781, 2021). "Considering the multitude of functions performed by Ca2+-binding proteins, the structural alterations induced by filling of their Sr2+-selective sites may rationalize the variety of the side effects of strontium ranelate accompanying osteoporosis treatment (see Section 1)." (PMID 34439824, 2021). "Carbonic anhydrase 2 (CA 2) is an early feature of osteoclast differentiation, and CA2 may play an important role in osteoporosis, osteoclast differentiation, and bone resorption and is associated with bone differentiation-related proteins." (PMID 34803683, 2021).
schizophrenia (12 papers, 2014 to 2023). A major psychotic disorder characterized by abnormalities in the perception or expression of reality. "Most of the gain-of-function mutations in Ca2+ channels are linked to psychiatric disorders with cognitive and social disorders like schizophrenia, bipolar disorder, depression and ASDs." (PMID 35013113, 2022). "That CA2 in the human hippocampus is critical to cognition, is supported by a meta-analysis of post-mortem studies, revealing that PV+ interneuron loss specifically within the CA2 is one the strongest predictors for schizophrenia and mood disorders." (PMID 34170374, 2021). "Further research into the cellular mechanisms that govern the CA2 may provide insight into the social deficits underlying certain neuropathologies, such as autism and schizophrenia, and potentially yield novel treatment strategies for these disorders." (PMID 31632251, 2019). "Similarly, a decrease in the number of CA2 interneurons, particularly PV-positive interneurons, has been associated with schizophrenia." (PMID 25309345, 2014). "This is reinforced by the findings of a lower number of CA2 inhibitory neurons in patients with schizophrenia and bipolar disorder." (PMID 36965045, 2023). "The results of our study present further similarities between CA2 functions and impairments seen in schizophrenia." (PMID 30387713, 2018). "Interestingly, altered CA2 neuronal activity was found in animal models of neurodevelopmental disorders like ASDs and schizophrenia or in sclerotic hippocampal tissue surgically excised from patients affected by temporal lobe epilepsy." (PMID 38298376, 2023). "Furthermore, CA2 is affected in a number of neuropsychiatric diseases, such as schizophrenia and bipolar disorder including animal models." (PMID 37603074, 2023). "We also found that CA2 activity contributes to gamma coherence between hippocampus and PFC and hippocampal ripple oscillations, suggesting that CA2 may play a role in the pathophysiology of schizophrenia." (PMID 30387713, 2018).
Alzheimer disease (11 papers, 2008 to 2025). A progressive, neurodegenerative disease characterized by loss of function and death of nerve cells in several areas of the brain leading to loss of cognitive function such as memory and language. "NF-H and MAP2 are substrates of the Ca2+-dependent cysteine protease, calpain, the levels of calpain are increased in the brains of patients with Alzheimer's disease." (PMID 18706097, 2008).
heart failure (11 papers, 2009 to 2025). Inability of the heart to pump blood at an adequate rate to meet tissue metabolic requirements. "Violin plots illustrating inter-subpopulation disparities indicated that C0 NAP1L1+ TCs and C2 MKI67+ TCs possessed considerably elevated heart failure scores, whereas C1 CA2+ TCs demonstrated moderate values, and C3 ITLN1+ TCs displayed the lowest scores." (PMID 40842994, 2025). "Increased cardiac Ca2+/calmodulin-dependent kinase II (CaMKII) expression and activity plays a role in heart failure development and progression by increasing class I HDAC activity." (PMID 35502901, 2022). "DPP-4 inhibition might exacerbate the clinical course of heart failure via pathways of SDF-1 (stromal cell-derived factor 1)/CaMKII (Ca2+/calmodulin-dependent protein kinase II)." (PMID 31969144, 2020). "Accordingly, we tested the hypothesis that heart failure induced by transverse aortic constriction (TAC) is associated with an increase in CaMKIIδB activity, an imbalance of Ca2+-handling proteins and altered Ca2+ homeostasis." (PMID 21931829, 2011). "However, little is known about the relationship between aberrant CaMKIIδB expression and the cross talk of Ca2+-handling proteins during heart failure." (PMID 21931829, 2011). "Likewise, ca2 mRNA and protein expression was also found to increase during the progression of ventricular hypertrophy in human, suggesting that ca2 could be a prognostic marker of heart failure." (PMID 25280539, 2014). "We therefore consider that ping waves are most likely to occur under conditions such as those found in heart failure where the RyRs are believed to have increased leakiness, SR Ca2+ load is reduced, diastolic Ca2+ levels may be elevated and Ca2+ pumps are less effective at removing cytosolic Ca2+." (PMID 22934033, 2012). "The cardiac failure scores were significantly elevated in C0 NAP1L1+ TCs (stage II), C1 CA2+ TCs (stage II), and C2 MKI67+ TCs (stage II)." (PMID 40842994, 2025).